CCK (cholecystokinin)
Diseases named in the same sentence as CCK in open-access papers (continued):
Sharing a sentence is not in itself a finding about the gene and the disease.
gastroparesis (2 papers, 2009 to 2021). Paralysis of the muscles of the stomach wall resulting in delayed emptying of the gastric contents into the small intestine. "It is still unknown whether this disturbance is primary or secondary to gastroparesis or depends on dysfunction in the CCK-oxytocin interaction, intrinsic gastric nerves, the vagal nerve, or in regulation of other hormones." (PMID 19243587, 2009).
Giardia infections (2 papers, 2015 to 2022). "The peptide hormone cholecystokinin (CCK) is induced during Giardia infections resulting in smooth muscle contractions mediated via mast cells." (PMID 35573800, 2022). "Taken together these data suggest that increased CCK release in giardiasis could be responsible for the symptoms." (PMID 26635531, 2015). "CCK plays a pivotal role in the regulation of digestive function and particularly in intestinal motility by stimulating cholinergic and afferent vagal fibers, suggesting that CCK may stimulate neuronal afferents in giardiasis." (PMID 26635531, 2015).
hyperlipidemia (2 papers, 2012 to 2025). "In addition, we observed that CCK-induced hyperlipidemia was accompanied by increased plasma levels of both apoB48 and apoB100." (PMID 23300532, 2012).
melanoma (2 papers, 2022 to 2023). A malignant, usually aggressive tumor composed of atypical, neoplastic melanocytes. "We then evaluated the expression levels of CCK mRNA through RT-PCR and found that CCK mRNA was detected in all melanoma and SCC cells." (PMID 36262666, 2022). "We confirmed that CCKAR+ and CCK+ cells were melanoma cells by staining these specimens with antibodies against the common markers of melanoma, HMB-45 and Melan A." (PMID 36262666, 2022). "CCK was detected in three of five cases of superficial spreading melanoma and two of five cases of acral melanoma." (PMID 36262666, 2022). "Furthermore, melanoma cell growth was recently shown to be suppressed by cholecystokinin/gastrin (CCK) receptor antagonists." (PMID 38069171, 2023). "First, we determined the expression levels of CCKAR and CCK in melanoma skin specimens." (PMID 36262666, 2022). "Melanoma cell growth was recently shown to be suppressed by cholecystokinin/gastrin (CCK) receptor antagonists, and our preliminary data suggested that melanoma patients with Helicobacter gastritis (which is associated with elevated serum gastrin) might have an increased risk of cancer progression." (PMID 38069171, 2023). "However, it remains to be clarified whether the CCK/CCK receptor signaling directly affects the growth of other melanoma cell lines." (PMID 36262666, 2022). "However, it remains unknown whether CCK and its receptors are involved in the progression of various types of skin cancer, such as melanoma." (PMID 36262666, 2022). "RT-PCR analysis showed that melanoma and SCC cell lines expressed the CCK mRNA." (PMID 36262666, 2022). "HMB-45‒expressing clinical melanoma and A375 melanoma cells coexpressed genes for CCKAR and CCK." (PMID 36262666, 2022). "First, melanoma and SCC cells pathologically employ CCK–CCK receptor engagement for tumor growth." (PMID 36262666, 2022).
neuropathic pain (2 papers, 2013 to 2020). Chronic pain caused by damage to nerve fibers. "Some studies have suggested that the effects of opioid-mediated analgesia in neuropathic pain may be reduced by an increase in neuropeptide cholecystokinin, an endogenous inhibitor of opioid-mediated analgesia." (PMID 31936282, 2020).
rheumatoid arthritis (2 papers, 2015 to 2024). A chronic, systemic autoimmune disorder characterized by inflammation in the synovial membranes and articular surfaces. "In a white rabbit model of rheumatoid arthritis, buccal acupuncture effectively relieved the pain by affecting the release of β-endorphin (β-EP) and cholecystokinin octapeptide (CCK-8) in cerebrospinal fluid." (PMID 38984037, 2024). "Several research groups have proved the anti-inflammatory effect of BV in several disease models such as a mouse model of Parkinson’s disease, Freund’s adjuvant-induced rheumatoid arthritis (RA) model, and cholecystokinin octapeptide-induced acute pancreatitis rat model." (PMID 26112466, 2015).
status epilepticus (2 papers, 2013 to 2024). Status epilepticus is defined as a continuous seizure lasting more than 30 min, or two or more seizures without full recovery of consciousness between any of them. "CCK+/CB1R+ axons in CA1-3 begin to degenerate within hours of status epilepticus, whereas PV+ INs are unaffected in this model." (PMID 38179984, 2024). "Interneurons stained by an antibody against CCK were significantly (p < 0.01) reduced in 3-week-old rats at day 3 after pilocarpine treatment, but counts of these interneurons were comparable to control values at days 7 and 14 after status epilepticus." (PMID 24009554, 2013). "Interestingly, these results highlight a different age-related sensitivity of CCK interneurons to pilocarpine-induced status epilepticus by confirming an enhanced resilience to damage in young animals." (PMID 24009554, 2013).
temporal lobe epilepsy (2 papers, 2022 to 2024). A localization-related (focal) form of epilepsy characterized by recurrent seizures that arise from foci within the temporal lobe, most commonly from its mesial aspect. "Supporting these results, CCK+/CB1R+ interneurons in the hippocampus are selectively lost in models of temporal lobe epilepsy with recurrent seizures induced by pilocarpine." (PMID 38179984, 2024). "In particular, the dorsal dentate gyrus and CA3 somatostatin-positive neurons and dorsal lateral septum cholecystokinin-positive neurons are selectively vulnerable to damage after temporal lobe epilepsy." (PMID 35571372, 2022).
abortion (1 paper, 2025). the ending of pregnancy by removing a fetus or embryo before it can survive outside the uterus. "Furthermore, it has been demonstrated that a deficiency in CCK is associated with gonadal abortion in zebrafish and medaka." (PMID 39851506, 2025).
acoustic neuroma (1 paper, 2017). A type of benign brain tumor that begins in the Schwann cells, which produce the myelin that protects the acoustic nerve - the nerve of hearing. "Cerebral gliomas, astrocytomas, and acoustic neuromas also express CCK." (PMID 28450850, 2017).
age-related hearing loss (1 paper, 2025). "CCK-mediated plasticity holds promise as a treatment strategy to enhance the effectiveness of late cochlear implants in prelingually deaf children and may serve as a basis for future non-invasive therapies targeting age-related hearing loss." (PMID 41264484, 2025).
alcohol abuse (1 paper, 2025). The use of alcoholic beverages to excess, either on individual occasions ("binge drinking") or as a regular practice. "Importantly, existing research has demonstrated a substantial involvement of CCK neurons in the regulation of substance abuse behavior, including alcohol abuse, through their heightened sensitivity to various stress factors, including ELS." (PMID 40114019, 2025).
alcohol addiction (1 paper, 2023). "Hence, regulating the balance of gut microbiota and the endogenous CCK may be a potential strategy for reducing the risk of relapse in alcohol addiction patients." (PMID 37962470, 2023). "Hence, regulating the balance of gut microbiota and the endogenous CCK or CCKR may be a potential strategy for reducing the risk of relapse in alcohol addiction patients." (PMID 37962470, 2023). "Our results demonstrate that AD patients developed gut bacterial and fungal microbiota dysbioses and the gut microbiota may be involved in the development of alcohol addiction by regulating the endogenous cholecystokinin and related receptors’ expression." (PMID 37962470, 2023). "However, in this study, we did not further deeply investigate the related function of CCK/CCKR changes induced by gut microbiota in the development of alcohol addiction, which is a weakness for our present work." (PMID 37962470, 2023). "However, previous research mainly focused on the role of alcohol-induced changes in CCK and its receptors in alcohol addiction but did not involve the gut microbiota." (PMID 37962470, 2023).
anterograde amnesia (1 paper, 2024). "It is reasonable to speculate that the reduced CCK level causes deficiency in recent memory or anterograde amnesia." (PMID 38750512, 2024).
Arthritis (1 paper, 2014). Inflammation of a joint. "There is also evidence that altered expression of the neuropeptide cholecystokinin (CCK) in the ACC is associated with the induction of arthritis in rodents." (PMID 24829554, 2014).
autism spectrum disorder (1 paper, 2021). A spectrum of developmental disorders that includes autism, and Asperger syndrome. "We propose that a better understanding of the physiological functions of the two NECAB proteins and CB1/CCK-positive interneurons in general will also provide important insights into the aberrant circuit mechanism in autism spectrum disorders." (PMID 33230531, 2021).
bile reflux (1 paper, 2023). "An increase in cholecystokinin may facilitate sphincter relaxation, bile excretion and common bile duct pressure regulation, while an increase in gastrin may relax the pyloric sphincter, exacerbate the bile reflux and cause elevated bile acid levels in the gastric juice." (PMID 37920676, 2023).
biliary dyskinesia (1 paper, 2021). A motility disorder characterized by biliary colic, absence of gallstones, and an abnormal gallbladder ejection fraction. "This regional disparity may reflect the low diagnostic accuracy of HIDA scintigraphy for gallbladder and biliary dyskinesia; however, past studies suggest that CCK-provoked HIDA scintigraphy can predict therapeutic benefit after cholecystectomy for patients with an abnormal GBEF." (PMID 33569543, 2021).
biliary tract disease (1 paper, 2020). "We argue that liver resection also damages the microstructure of the biliary tract and its response to cholecystokinin in donors, thus impairing the motility of the biliary tract and increasing the risk of biliary tract disease following liver donation." (PMID 32226025, 2020).
brain tumors (1 paper, 2013). "Recently, receptors for CCK and gastrin were detected in large amounts in the tissues of lung, ovarian, thyroid, and brain tumors." (PMID 24368955, 2013).
celiac disease (1 paper, 2023). An autoimmune genetic disorder with an unknown pattern of inheritance that primarily affects the digestive tract. "The peptide hormone levels of cholecystokinin (CCK, from I cells), glucose-dependent insulinotropic polypeptide (GIP, from K cells), and GLP-1 (from L cells) are reduced in the blood of celiac disease patients." (PMID 37240181, 2023).
cerebral infarction (1 paper, 2020). An ischemic condition of the brain, producing a persistent focal neurological deficit in the area of distribution of the cerebral arteries. "Moreover, higher serum levels of SP were associated with the mortality in patients suffering from severe acute ischemic stroke, and CCK was involved in the regulation of the brain-gut axis in the treatment of cerebral infarction." (PMID 32410857, 2020). "Moreover, higher serum levels of SP were reported to be associated with the mortality in patients suffering from severe acute ischemic stroke, and CCK was involved in the brain-gut axis in the treatment of cerebral infarction." (PMID 32410857, 2020).
cholecystolithiasis (1 paper, 2021). Single or multiple, ovoid or irregular, solid particles that are formed from bile, cholesterol, and calcium in the gallbladder cavity. "The mechanisms of post-operative cholecystolithiasis might be similar to that for AAC in this study: the abnormal secretion of CCK and the abnormal biliary secretion." (PMID 34485348, 2021).
Cirrhosis (1 paper, 2009). A chronic disorder of the liver in which liver tissue becomes scarred and is partially replaced by regenerative nodules and fibrotic tissue resulting in loss of liver function. "On the other hand, patients with cirrhosis show raised serum bile salt concentrations which directly inhibit CCK-induced gallbladder contraction, contributing to the impairment of gallbladder emptying." (PMID 19680454, 2009). "Under physiological conditions, the gallbladder contractile activity is primarily regulated by CCK, whose levels are often increased in cirrhosis." (PMID 19680454, 2009).
colon cancer (1 paper, 2016). "Since activation of CCKBR has recently been shown to promote the stemness of colon cancer cells, it is possible that the induction of CCK expression by adipocytes may lead to the activation of an autocrine loop and as a result promote CSC self-renewal." (PMID 26700819, 2016).
colorectal tumor (1 paper, 2020). "Local or systemic originated-CCK might influence the growth of colorectal tumor." (PMID 32210918, 2020).
diabetic nephropathy (1 paper, 2020). "We hypothesize that changes in the gut microbiota in diabetic db/db mice (untreated and CKK- and PFD-treated) compared to lean db/m mice allow for insights into the role of gut microbes in diabetic nephropathy and potentially beneficial effects associated with PFD and CCK treatments." (PMID 32899353, 2020).
enteritis (1 paper, 2013). Inflammation of the small intestine. "Proximal enteritis induced by T. spiralis has been associated with a period of hypophagia and an increase in CCK and serotonin secreting EECs." (PMID 23349631, 2013). "We have characterized these two phases using genetically modified mice lacking functional CCK or adaptive immunity and demonstrated that CD4+ T-cells drive I-cell hyperplasia and the resulting CCK is an essential mediator of the initial hypophagia observed during enteritis." (PMID 23349631, 2013). "The enteroendocrine I-cell derived hormone cholecystokinin is an essential mediator of initial hypophagia and is induced by CD4+ T-cells during enteritis." (PMID 23349631, 2013). "However, the absence of CCK during this I-cell hyperplasia resulted in the complete absence of initial hypophagia in CCKlacZ mice, despite comparable enteritis." (PMID 23349631, 2013). "Furthermore, increased I-cell function, through the release of CCK, is essential for the initial hypophagia during enteritis, but not the secondary episode during peripheral myositis." (PMID 23349631, 2013).
enterocolitis (1 paper, 2017). An inflammatory process affecting the small intestine and colon. "For example, cholecystokinin (CCK) and dopamine receptor agonists were found to reduce enterocolitis-associated inflammation, thus providing a new therapeutic target." (PMID 28961226, 2017).
epileptic encephalopathies (1 paper, 2021). "Furthermore, as GluN2D de novo mutations have also been linked to epileptic encephalopathies, and given the clear role of this subunit in CCK IN synaptic function, the heterogeneity may explain the selective loss of these neurons in some forms of experimental epilepsy." (PMID 34326063, 2021).
esophageal tumor (1 paper, 2020). "Local or systemic originated-CCK might influence growth of esophageal tumor." (PMID 32210918, 2020). "Local or systemic originated-CCK might influence the growth of esophageal tumors." (PMID 32210918, 2020).
esophagitis (1 paper, 2011). An acute or chronic inflammatory disease affecting the esophageal wall. "Three RCTs were excluded, as they did not analyze the parameters for which we sought to analyze (e.g., postoperative complications or the incidence of reflux symptoms or esophagitis or gastritisl), but rather compared cholecystokinin, bacterial counts and total bile acid concentrations over 24 h." (PMID 23554676, 2011).
fragile X syndrome (1 paper, 2014). A genetic syndrome caused by mutations in the FMR1 gene which is responsible for the expression of the fragile X mental retardation 1 protein. "Endocannabinoid modulation of CCK+ cells may underlie some of the deficits in oscillations in Fragile X Syndrome (FXS)." (PMID 25249974, 2014).
gastric adenocarcinoma (1 paper, 2020). "Gastrin but not CCK promotes growth of human gastric adenocarcinoma cells." (PMID 32210918, 2020).
gastric ulcer (1 paper, 2023). An ulcerated lesion in the mucosal surface of the stomach. "Meanwhile, the beneficial effects of several peptides (i.e., amylin, cholecystokinin, leptin, and stable gastric pentadecapeptide BPC 157, suggested as an acting mediator of the dopamine brain-gut axis) were included in the dopamine gastric ulcer story." (PMID 38139825, 2023). "Meantime, the beneficial effects of several peptides (i.e., amylin, cholecystokinin, leptin, and stable gastric pentadecapeptide BPC 157 (suggested as the acting mediator of the dopamine brain-gut axis)) further extended the dopamine gastric ulcer story." (PMID 38139825, 2023).
gastritis (1 paper, 2013). Inflammation of the stomach. "This suggests that either the regulation of HGL secretion by GLP-1 and CCK is abnormal in gastritis or there exists another factor with higher potential for regulation of the secretion and activity of HGL." (PMID 23899880, 2013). "We conclude that the regulation of HGL secretion by GLP-1 and CCK is altered in patients with gastritis." (PMID 23899880, 2013). "Regulation of HGL activity by GLP-1 and CCK is abnormal in patients with gastritis." (PMID 23899880, 2013).
gastrointestinal infection (1 paper, 2013). "Furthermore, we demonstrate for the first time an immunoendocrine feedback loop, in which CD4+ T-cell driven weight loss via CCK reduces leptin levels which impinge on CD4+ T-cell driven effector mechanisms for gastrointestinal infection resolution." (PMID 23349631, 2013).
helminth infection (1 paper, 2025). "Cholecystokinin (CCK), a hormone secreted by a subset of EECs in response to luminal nutrients, is involved in resolving helminth infection." (PMID 40051209, 2025).
hyperandrogenism (1 paper, 2024). Excessive secretion of androgens from the adrenal glands or gonads. "Hyperandrogenism, IR, the reduced secretion of cholecystokinin postprandially, and leptin resistance defined by leptin receptors’ knockout in the hypothalamus have been implicated in the pathogenesis of hypothalamic dysfunction and appetite dysregulation." (PMID 38613082, 2024).
hypersensitivity pneumonitis (1 paper, 2012). Hypersensitivity pneumonitis (HP) is a pulmonary disease with symptoms of dyspnea and cough resulting from the inhalation of an antigen to which the subject has been previously sensitized. "cCK-18 was measured in serum from subjects with IPF, hypersensitivity pneumonitis (HP), nonspecific interstitial pneumonia (NSIP), and control subjects." (PMID 23167970, 2012).
hyperthyroidism (1 paper, 2025). Overactivity of the thyroid gland resulting in overproduction of thyroid hormone and increased metabolic rate. "Additionally, hyperthyroidism increases bile acid secretion, and reduces gallbladder contractility in response to cholecystokinin, thereby promoting bile stasis and cholesterol supersaturation." (PMID 41181799, 2025).
intestinal tumor (1 paper, 2026). "Additionally, β-adrenergic receptors have been identified in the secretory intestinal tumor cell line (STC-1), where they may enhance CCK release via a calcium-dependent mechanism." (PMID 41550979, 2026).